NAA35 (N-alpha-acetyltransferase 35, NatC auxiliary subunit)
Description:
Auxillary component of the N-terminal acetyltransferase C (NatC) complex which catalyzes acetylation of N-terminal methionine residues. N-terminal acetylation protects proteins from ubiquitination and degradation by the N-end rule pathway. Involved in regulation of apoptosis and proliferation of smooth muscle cells.
Synonyms: EGAP; MAK10; FLJ21613; FLJ22643; bA379P1.1; MAK10P
Tractability: Small molecule: a structure with a bound ligand is known. Antibody: its Gene Ontology location is reachable by antibodies, with high confidence. PROTAC: ubiquitination databases record sites on it; its protein half-life has been measured.
Gene: Protein-coding gene on chromosome 9 (85,941,002 to 86,026,967, forward strand). Ensembl gene ENSG00000135040.
Subcellular location: Cytoplasm
Subcellular location (Human Protein Atlas): Cytosol; Nucleoplasm; Plasma membrane
Pathways (Reactome):
Vesicle-mediated transport: Retrograde transport at the Trans-Golgi-Network
Gene Ontology:
Molecular function: protein binding
Biological process: negative regulation of apoptotic process; smooth muscle cell proliferation
Cellular component: cytoplasm; cytosol; NatC complex
Genetic constraint (gnomAD): Loss-of-function variants: 8 observed, 53.34 expected, observed/expected ratio (o/e) 0.15, 90% interval 0.087 to 0.27. The upper end of that interval is the gene's LOEUF score, 0.27, which puts it in group 1 of 6, group 1 being the genes least tolerant of losing a copy. Missense variants: 338 observed, 541.96 expected, observed/expected ratio (o/e) 0.62, 90% interval 0.57 to 0.68. Synonymous variants: 161 observed, 167.78 expected, observed/expected ratio (o/e) 0.96, 90% interval 0.84 to 1.09.
Homologues: Orthologues: chimpanzee NAA35 (100% identical), macaque NAA35 (99% identical), dog NAA35 (99% identical), rabbit NAA35 (99% identical), pig NAA35 (98% identical), mouse Naa35 (97% identical), rat Naa35 (97% identical), guinea pig NAA35 (96% identical), tropical clawed frog naa35 (91% identical), zebrafish naa35 (86% identical), Drosophila melanogaster Naa35 (40% identical), Caenorhabditis elegans natc-1 (27% identical).
Diseases named in the same sentence as NAA35 in open-access papers:
NAA35 is named in the same sentence as 10 diseases in open-access papers, as found by Europe PMC text mining. Sharing a sentence is not in itself a finding about the gene and the disease. The quoted sentences say what the papers report.
tumor (5 papers, 2013 to 2023). "The molecules that were differentially expressed in tumor and normal tissues by R software analysis were TMEM79, SMG5, NAA35, SLC45A3, FLG, TMEM254." (PMID 37936239, 2023). "Six genes overlapped in the three top 50 lists for tumor response, overall clinical response, and PFS, including MAGOH, C16orf87, ORC1, NAA35, PWP2, and SIAH2." (PMID 35892846, 2022).
NAA35 also shares sentences with these, for which no sentence is quoted: esophageal squamous cell carcinoma (5 papers); esophageal cancer (3); prostate carcinoma (3); Bladder cancer (2); cervical cancer (2); colorectal cancer (2); cancer (1); lymph node metastasis (1); non-small cell lung carcinoma (1).